MPO (myeloperoxidase)
Diseases named in the same sentence as MPO in open-access papers (continued):
Sharing a sentence is not in itself a finding about the gene and the disease.
Sepsis (continued). "For MPO however, levels of MPO were higher in the sepsis group (166 (14–3375) ng/ml versus 84 (15–2611) ng/ml in non-sepsis, P = 0.011)." (PMID 24438360, 2014). "Involvement of MPO has also been reported in various diseases like ischemia-reperfusion injury, severe sepsis, acute lung injury (ALI), and acute respiratory distress syndrome (ARDS)." (PMID 23110185, 2012). "In the lung of caPI3K CLP mice we observed a pattern of MPO activity that closely mirrored the serum KC response to sepsis." (PMID 23028587, 2012). "To evaluate the effect of transgenic p110α on neutrophils in sepsis, we examined tissue MPO activity as an indicator of tissue neutrophil infiltration and accumulation." (PMID 23028587, 2012). "Because organ dysfunction is considered to be the end point of damage caused by the excessive inflammatory response of sepsis, we therefore examined the level of AST and ALT, MPO activity, cytokine production, and histology during sepsis." (PMID 21826187, 2012). "The lipid peroxide level increased in the lung, heart, liver, and kidney tissues after CLP-induced sepsis, and myeloperoxidase activity increased in the lung, heart, and liver tissues." (PMID 21789470, 2011). "In the absence of GR159897, vehicle-treated mice showed signs of polymicrobial sepsis with elevated MPO activity and lung chemokine and cytokine levels." (PMID 21188216, 2010). "Conversely, TEA led to an increased bradykinin-induced pulmonary vasoconstriction and pulmonary edema despite reduced exNO levels and pulmonary MPO activity in hypodynamic sepsis (each P < 0.05 versus CLP 24 h)." (PMID 19580652, 2009). "Many of the immunological markers discussed in this review, such as interleukin-6 (IL-6), tumor necrosis factor-alpha (TNF-α), interleukin-1 beta (IL-1β), and myeloperoxidase (MPO), have been extensively studied in the contexts of sepsis, cardiovascular disease, or general critical illness." (PMID 40710793, 2025). "Given the potential role of NETs in driving excessive inflammation and coagulation activation during sepsis, we assessed key NETs components in septic mice, including cell‐free DNA (cfDNA), myeloperoxidase (MPO), neutrophil elastase (NE) and citrullinated histone H3 (CitH3)." (PMID 40779122, 2025). "Elevated levels of GSDMD-NETs axis biomarkers (N-GSDMD and MPO-DNA) were significantly associated with the incidence of SIC, mechanical ventilation requirement, and in-hospital mortality in sepsis patients, demonstrating a significant relationship with glycocalyx damage." (PMID 40766307, 2025). "MPO, NE, cfDNA, citH3 and other NET-related biomarkers should be investigated in RCTs for their diagnostic and prognostic accuracy in sepsis and sepsis-related thrombotic events and other complications to define their cut-offs and diagnostic and prognostic value." (PMID 40731775, 2025). "Overall, our study highlights the complex role of NETs formation, suggesting that higher levels of CIT-HIST-H3 have a more detrimental effect on sepsis-induced inflammation and coagulopathy (immunothrombosis) than MPO, opening avenues for future research and potential treatments." (PMID 41476244, 2025). "Multivariate logistic regression analysis identified MPO, HOCl, tumor necrosis factor-α (TNF-α), white blood cells (WBC), and the Acute Physiology and Chronic Health Evaluation II (APACHE II) score as independent risk factors for NOAF in sepsis." (PMID 39030470, 2024). "This study suggests a critical role of LTF, LCN2, ELANE, MPO and CEACAM8 in sepsis and may provide potential diagnostic biomarkers and therapeutic targets for the treatment of sepsis." (PMID 38912048, 2024). "Finally, after multivariate logistic regression analysis, MPO, HOCl, TNF-α, WBC, and APACHE II score were identified as independent risk factors for NOAF in sepsis." (PMID 39030470, 2024).
Sepsis (continued). "We therefore evaluated potential differences in neutrophil infiltration in the peritoneal cavity and lung of neonate and adult mice exposed to CS-induced sepsis, via measuring absolute neutrophil numbers in the peritoneal cavity and myeloperoxidase (MPO) activity in lung tissue lysates." (PMID 38263289, 2024). "To explore the diagnostic roles of MPO-DNA and cf-DNA in sepsis versus non-sepsis, we conducted a logistic regression analysis on these two patient groups." (PMID 39457503, 2024). "This indicates that the abnormal elevation of circulating MPO-DNA levels may be involved in the progression of coagulation abnormalities in sepsis patients, promoting abnormal thrombosis formation." (PMID 39457503, 2024). "According to our findings, sepsis patients had higher levels of MPO expression in peripheral blood mononuclear cells, which is consistent with other studies, suggesting that MPO has the potential to serve as a biomarker to distinguish sepsis from infection-negative systemic inflammation." (PMID 38912048, 2024). "Although MPO-DNA was not identified as an independent risk factor for sepsis, we still generated an ROC curve for it due to its suggestive role in the prognosis of sepsis." (PMID 39457503, 2024). "Notably, we identified five key genes (LTF, LCN2, ELANE, MPO, CEACAM8) associated with sepsis using the intersections of the top genes identified by cytoHubba and greenyellow module genes of the WGCNA." (PMID 38912048, 2024). "In addition, human neutrophils include a unique plasmenylethalonamine pool that undergoes myeloperoxidase-dependent oxidation during activation and is elevated in the plasma during sepsis." (PMID 39209813, 2024). "Moreover, sepsis patients also presented notably increased histone H3, myeloperoxidase (MPO), angiopoietin-2 and endocan levels in the blood, and such increase was positively correlated with the number of EVs." (PMID 37559007, 2023). "Additionally, echinacoside mitigated the elevated activity of MPO induced by sepsis, the increase of the lung W/D ratio, as well as the elevated levels of total protein in BALF and the increased numbers of macrophages and neutrophils." (PMID 38001778, 2023). "The only differences we could observe were in the MPO concentration between sepsis COVID and sepsis patients, and we argue that this is a result of the generally higher neutrophil count in bacterial induced sepsis." (PMID 36969221, 2023). "Increased MPO activity (considered to be a marker of neutrophilic presence) in the cerebral cortex of sepsis survivor mice could be due to increased IL-17A levels." (PMID 37175808, 2023). "Increased MPO-DNA levels on days 3 and 7 during sepsis hospitalization were associated with decreased mean arterial pressure, a lower PaO2/FIO2 ratio, an increased sepsis-related organ failure assessment (SOFA) score, and 28-day mortality." (PMID 37081895, 2023). "In addition, MPO and LCN2 have been identified as critical genes in sepsis and sepsis-related ARDS, with LCN2 showing diagnostic value in sepsis-related ARDS." (PMID 37822934, 2023). "We only found statistical difference (p = 0.045) in using MPO as a distinguisher of sepsis and sepsis COVID, while the PDL1 concentration could not statistically differentiate sepsis, sepsis COVID, and septic shock." (PMID 36969221, 2023). "Moreover, a further up-regulation of histone H3 and MPO appeared in sepsis rats after injection of PEVs." (PMID 37559007, 2023). "They rejected the prognostic utility of cfDNA in trauma, due to lower levels in trauma patients compared to sepsis, even though citrullinated histone H3 and myeloperoxidase (MPO), as relevant markers of NETosis, were higher in trauma patients than in the control group." (PMID 36980458, 2023).
Sepsis (continued). "Limited investigations revealed that BBR inhibits LPS-induced oxidative stress markers NO protein and iNOS expression in RAW 264.7 and THP-1 macrophage cells and further alleviates ALT, AST, malondialdehyde (MDA), and myeloperoxidase (MPO) activity in sepsis rat model." (PMID 36741234, 2023). "Interestingly, in both organs, treatment with PF271 abolished the increase in MPO-staining induced by experimental sepsis." (PMID 35178052, 2022). "NETs can also be detected in human serum as double strand-DNA combined with myeloperoxidase (MPO) by ELISA and their levels are reported to be elevated in patients with various inflammatory diseases such as acute lung injury, sepsis and Covid-19 infection as well as thrombosis." (PMID 35756123, 2022). "Increased serum MPO activity has been identified as an indicator of inflammation and sepsis." (PMID 35158641, 2022). "Sepsis and septic shock are also characterized by increased neutrophil protease levels, i.e., neutrophil elastase, fibrin and matrix metalloproteinases, and MPO, which results in production of WARS." (PMID 36499104, 2022). "Therefore, the results suggested that in the intestinal tissues of burn sepsis mice, the activation of BTK was closely associated with the activity of MPO." (PMID 35280898, 2022). "Sepsis-induced MPO activity was reduced in male CLP P2Y12 KO and CLP P2Y1 KO female mice." (PMID 36405709, 2022). "Results showed an average MPO level of 60 ng/mL in sepsis patients and 43 ng/mL in SIRS patients." (PMID 36147548, 2022). "Neutrophils are involved in sepsis and MPO activity is used to investigate neutrophil infiltration." (PMID 35774785, 2022). "LFM-A13 also reduced the histopathological changes and cellular apoptosis in intestinal tissues, inhibited the inflammatory cytokines IL-4, IL-6, and TNF-α in serum and intestinal tissues, and significantly inhibited the increase in intestinal MPO activity induced by burn sepsis." (PMID 35280898, 2022). "To evaluate the effects of Lav pre-treatment on sepsis-induced oxidative stress in rats, we determined the levels of the oxidative stress injury indicators MPO and MDA, as well as the antioxidant stress injury indicators SOD and GSH in the collected lung tissues." (PMID 35588105, 2022). "Our experimental results show that the CLP procedure conduced to pulmonary histopathological alteration, accumulation of neutrophils and macrophages in the BALF, enhance MPO activity, and increase survival percentage, which indicated that the sepsis-induced ALI model was successfully established." (PMID 35153740, 2021). "In a model of CLP-induced sepsis in rats, administration of sildenafil 8 h after the insult elevated a renal blood flow and decreased the plasma levels of creatinine, lactate, and creatine kinase, and lung myeloperoxidase." (PMID 33669167, 2021). "In addition, our study further revealed the hypomethylation of MPO gene, coding for myeloperoxidase, which has previously been described as a potential marker of mortality in sepsis." (PMID 33659006, 2021). "We hypothesised that baseline plasma levels and kinetics of IL-6, IL-8, HBP and MPO differ depending on the phase of sepsis." (PMID 33461369, 2021). "Next, we determined the MPO-DNA levels in the late stage of sepsis." (PMID 34759282, 2021). "The TBARS, protein carbonyl contents, and MPO activity in the diaphragm were increased significantly in rats in the sepsis group compared to rats in the sham group 24 h after surgery (P < 0.01), while the increase was partially restored after NRG-1β treatment (P < 0.01, P < 0.05)." (PMID 32765805, 2020). "It was reported that acupuncture at ST36 significantly decreased alanine aminotransferase (ALT) and aspartate aminotransferase (AST), attenuating sepsis-induced hepatic injury by reducing the tissue water content of liver and suppressing hepatic inflammatory cytokines (iNOS, MPO, and TNF-α)." (PMID 32215037, 2020).
Sepsis (continued). "MPO is enriched in neutrophils and well accepted to be an indicator of inflammation in sepsis." (PMID 33324396, 2020). "However, both male and female KO mice exhibited a significant elevation of MPO after sepsis when compared to sex-matched WT septic mice." (PMID 32117320, 2020). "Interestingly, our study found that MPO activity of the diaphragm in the rats of the NRG group was significantly reduced compared to that of the sepsis group." (PMID 32765805, 2020). "However, despite higher MPO content in serum of sepsis patients, the addition of ABAH resulted only in a marginal increase of impedance values at the 6 h time point and was without effect at the 12 and 24 h time points." (PMID 32050431, 2020). "The MPO activity was used to assess the degree of inflammatory injury following sepsis." (PMID 33145344, 2020). "In terms of MPO content these findings are in line with a recent report, however, in contrast to the present study the authors reported comparable neutrophil numbers in sepsis and non-sepsis samples." (PMID 32050431, 2020). "MPO staining showed strong immunoreactivity in sepsis as compared to the control." (PMID 31817302, 2019). "Day 1 MPO levels were significantly higher in trauma and sepsis patients than in healthy controls." (PMID 31119471, 2019). "MPO is an indicator of neutrophil infiltration as well as severity of inflammation during sepsis." (PMID 31234591, 2019). "MPO was also overexpressed in sepsis animal tissue samples, as observed by IHC." (PMID 31817302, 2019). "The administration of BoxA significantly ameliorated sepsis-induced multiple organ damage at 24 h, 48 h, and 72 h after sepsis initiation as evidenced by the declining levels of serum biomarkers for organ dysfunction as well as decreasing lung oedema and MPO content." (PMID 30881224, 2019). "Intracerebroventricular (ICV) injection of BoxA significantly ameliorated multiple organ damage, as shown by decreased serum levels of ALT, AST, CG, CK, CK-MB, BUN, and Cr, as well as reduced MPO activity and W/D ratio of pulmonary tissues when compared with those of the sepsis group." (PMID 30881224, 2019). "In summary, we reported a novel function of CIRP to generate NETs in the lungs during sepsis evidenced by flow cytometric analysis identifying CitH3 and MPO double positive neutrophils as NETs and by showing PAD4 upregulation in neutrophils or lung homogenates." (PMID 31000768, 2019). "During sepsis, free radical species and MPO production exceed antioxidant defenses." (PMID 31817302, 2019). "There was a significant effect of CLP-induced sepsis on the liver MPO activity." (PMID 31070531, 2018). "We show that myeloperoxidase is a potentially novel biomarker for sepsis in the ICU." (PMID 28916973, 2017). "MPO activity in liver tissue was measured as an index to assess the extent of liver injury resulting from neutrophil infiltration during the progression of sepsis." (PMID 28067837, 2017). "However, it would be interesting to test both MPO activity and intra- and extracellular MPO levels concurrently during infection and/or sepsis." (PMID 28916973, 2017). "Additionally, our results indicated that MPO activity increased in both septic groups, and the activity increased higher in midgrade sepsis than in low-grade sepsis." (PMID 29230271, 2017). "In addition, the level of MPO in the KO-CLP sepsis group was significantly lower than in the WT-CLP sepsis group in the lung and liver (p < 0.05)." (PMID 28694565, 2017). "However, in severe bacterial infections such as sepsis, the activated neutrophils release large amounts of MPO for bactericidal activities, and an increase in degranulated neutrophils can reduce the MPXI values." (PMID 27902604, 2016).
Sepsis (continued). "A strategy utilizing the neutralizing Ab against OPN dramatically reduced systemic inflammatory responses, organ injuries, and neutrophil infiltration into the lungs, leading to the improvement of the integrity of lung architecture and downregulation of MPO activity after sepsis." (PMID 25887405, 2015). "Exogenous administration of Zn-MT-2 significantly decreased the MPO activities after burn sepsis." (PMID 26550025, 2015). "The MPO assay was performed to evaluate the neutrophil infiltration in liver and lung, the two organs that were among the mostly suffered from inflammatory damages after burn sepsis." (PMID 26550025, 2015). "In sepsis, activated neutrophils transmigrate and infiltrate into the lungs where they release a large number of proteolytic enzymes, such as myeloperoxidase (MPO), and reactive oxygen species (ROS) including hydrogen peroxide and superoxide for elimination of invaded pathogens." (PMID 25887405, 2015). "High serum concentrations of elastase and MPO over time were associated with non-survival, particularly in the no anticoagulation group in sepsis." (PMID 24438360, 2014). "It has been shown that MPO in myocardial tissue significantly increased in LPS-induced sepsis." (PMID 24371817, 2013). "Application of MPO inhibitors might therefore represent an attractive strategy to interfere with BBB breakdown in sepsis patients." (PMID 23691142, 2013). "Moreover, intravenous administration of honey protected against organ failure in rabbits following LPS-induced sepsis through the inhibition of inflammation and myeloperoxidase production." (PMID 23409104, 2013). "On the other hand, prophylactic as well as therapeutic administration of PAG significantly reduced sepsis-associated systemic inflammation, as evidenced by decreased MPO activity and histological changes in lung and liver, and attenuated the mortality in CLP-induced sepsis." (PMID 24278674, 2012). "Early in sepsis there was increased tissue content of MPO in a variety of organs." (PMID 23208733, 2012). "The level of plasma MPO, a key exocytotic enzyme in the neutrophils respiratory burst process, rose dramatically in the SCD-H animals to a level 10–12 times the baseline level at 3 and 6 hours after sepsis induction, whereas MPO levels were unchanged in the SCD-C animals." (PMID 21533222, 2011). "Notably, Siv@NMs treatment achieved significantly greater reductions in MPO-DNA, H3cit, TNFα, and IL-6 levels, further validating the enhanced therapeutic efficacy of the nanoparticle formulation in suppressing systemic NETosis and inflammation during sepsis." (PMID 40574078, 2025). "Furthermore, an alarming, combined increase in MPO and Histones—thresholds of > 84.9 ng/ml for MPO and > 126.4 ng/ml for Histones—could serve as an urgent warning to implement NETs inhibitors in sepsis management." (PMID 41476244, 2025). "Additionally, several clinical trials are currently investigating the therapeutic potential of targeting anti-MPO in various conditions, including sepsis, systemic lupus erythematosus, rheumatoid arthritis, small-vessel vasculitis, inflammatory bowel disease, cancer, and glomerulonephritis." (PMID 41476244, 2025). "This study highlights a concerning simultaneous increase in myeloperoxidase and histones (thresholds of > 84.9 ng/ml and > 126.4 ng/ml, respectively), which may serve as vital indicators indicating the urgent need for NETs inhibitors in sepsis treatment." (PMID 41476244, 2025). "However, the exact role of MPO in sepsis still requires further research." (PMID 38912048, 2024). "Moreover, network pharmacology indicated that oxidative stress and inflammation are associated with sepsis-induced ALI; therefore, we detected the expression of oxidative stress factors (MPO, ROS, MDA, and SOD) and inflammatory factors (TNF-α, IL-6, and IL-1β) in LPS-stimulated HUVECs." (PMID 38445620, 2024). "Moreover, MPO-DNA levels positively correlated with APACHE-II scores in patients with sepsis." (PMID 38888975, 2024).